LCN2 (lipocalin 2)
Diseases named in the same sentence as LCN2 in open-access papers (continued):
Sharing a sentence is not in itself a finding about the gene and the disease.
tumor (continued). "However, stromal/macrophage-expression of Lcn-2 correlated with tumor onset, lung metastases, and recurrence, whereas FPN did not." (PMID 33808732, 2021). "Furthermore, we observed a statistically nonsignificant increase in skeletal muscle mass in tumor-bearing Lcn2-KO mice compared to WT, while cardiac tissue was significantly spared in tumor-bearing Lcn2-KO mice." (PMID 33824339, 2021). "Consistent with Lcn2-KO tumor-bearing mice, ICV AgRP treatment did not alter ubiquitin-ligase or autophagy-related catabolic pathways in skeletal muscle or cardiac tissue, suggesting that improved caloric intake improves muscle mass through alternative pathways during cachexia." (PMID 33824339, 2021). "Thus, LCN2 may regulate different pathways, including cell cycle, MAPK, and mTOR proteins to promote tumor growth in IBC." (PMID 34342930, 2021). "Tumor cells increase iron uptake through the upregulation of divalent metal transporter-1 (DMT1), transferrin/transferrin-receptor (Tf/TfR), and lipocalin-2/lipocalin-2receptor (Lcn-2/Lcn-2R) systems, and its storage by ferritin (FT) heavy chain (FTH) and FTL overexpression." (PMID 32426284, 2020). "Interestingly, in the absence of PKP3, p38β is able to control the expression of LCN2, indicating a potential role of p38β in tumor formation." (PMID 33053909, 2020). "It has been reported that LCN2 can form a complex with matrix metalloproteinase-9 (MMP-9), thereby preventing MMP-9 degradation and enhancing its activity in vitro, which may also enhance tumor invasion." (PMID 31500632, 2019). "Adding to the concept of tumor as wounds that do not heal, it was reported that LCN2 from macrophages exposed to apoptotic cells and thus, linked to S1P signaling via S1PR3, supported the proliferation and healing of renal epithelium, once inflammatory conditions were terminated." (PMID 28804221, 2017). "This supports that Lipocalin 2 may be used as a biomarker at early stages of lung tumor development but not tumor progression." (PMID 28088789, 2017). "Interestingly, upregulated Lipocalin 2 is not correlated with any of other parameters including tumor size, lymph node, TNM stage, histopathological type, and smoking history." (PMID 28088789, 2017). "Overexpression of LCN2 promoted a mesenchymal-like cell morphology accompanied by increased expression of mesenchymal markers (Snail, Twist, N-cadherin, fibronectin and MMP9) that contribute to invasiveness, which accounts for their role in enhancing tumor cell motility in metastasis." (PMID 26840566, 2016). "Neither LCN2 nor MMP9 shows tumor-specific expression, and the release of these proteins into the circulation from other tissues of origin might therefore change as an adverse response to therapy." (PMID 27461255, 2016). "Thus, we examined the correlation between tumor volumes and plasma LCN2 levels in each of 5 mice bearing normoxic or hypoxic tumors." (PMID 25467539, 2014). "The relatively low correlation value indicates that tumor size may not be a crucial factor for the elevated plasma concentration of LCN2." (PMID 25467539, 2014). "Therefore, LCN2 appeared to be specifically expressed in hypoxic tumor cells, but not normal cells, even under hypoxic conditions." (PMID 25467539, 2014). "Thus, the interactions between LCN2 and EMT as well as angiogenesis seem to be complex and may be a function of tissue context, tumor type and tumor model." (PMID 22559235, 2012). "However, most studies of LCN2 function in tumors have been conducted in tumor cells rather than immune cells; therefore, the LCN2 expression pattern and functions in tumor-infiltrating T cells remain unclear." (PMID 38072118, 2023). "Moreover, Se-PC PDT treatment may dilute tumor metabolism and proliferation by depressing the activity of the glucose transporter GLUT1 (gene Slc2a1) and the iron transport-related factors LCN2 (gene Lcn2) and transferrin (gene Trf), which reduce the synthesis of hemoglobin and inhibit ferroptosis." (PMID 37994159, 2023).
tumor (continued). "Thus, in the absence of PKP3, p38β may control LCN2 expression, showing a potential role for p38β in tumor development." (PMID 35008796, 2021). "However, it is presently unclear whether the pro-tumor actions of Lcn-2 depend on its iron loading or not." (PMID 28979267, 2017). "Since overexpression of TCF7L1 predisposed DMBA/TPA treated skins to develop tumors at a higher rate but did not affect tumor size, it suggests that upregulation of LCN2 by TCF7L1 in the pre-tumor state may be facilitating the transitioning of mutated cells into tumor cells." (PMID 28467300, 2017). "Next, we assessed the levels of WTX-L/LCN2/ferroptosis-related proteins in tumor tissues via immunohistochemistry (IHC) staining of WTX, Ki67, 4-hydroxy-2-noneal (4-HNE), LCN2, and MDA." (PMID 40109379, 2025). "By stimulating human patient-derived tumor cells (T-TEC) in vitro with a mutant, non-iron-binding Lcn-2, the iron-binding capacity was disabled in comparison to normal non-modified protein, resulting in a significant reduction in the intracellular iron amount." (PMID 37958332, 2023). "Compared with responders who achieved a partial response after the administration of anti‐PD‐1 immunotherapy, nonresponders who demonstrated an enlargement of tumor size had higher PGAM1 and LCN2 expression as well as lower CD8 expression." (PMID 37705495, 2023). "Unlike what has been observed for LCN2 and MMP9, the SLC22A17 expression was downregulated in most tumor types (66.7%) compared to normal tissue samples." (PMID 36211450, 2022). "Unlike LCN2, SLC22A17 was predominantly downregulated in more than 75% of tumor types, showing statistical significance (FC ≥ 1.4 or ≤ −1.4; p ≤ 0.05) for the gene and seven of its isoforms." (PMID 36211450, 2022). "We found that the LCN2+ cells among CD45- cells, which are mainly tumor cells, did not change significantly after acute ischemic stroke." (PMID 32153594, 2020). "Therefore, to confirm whether LCN2 transcripts were expressed in hypoxic tumor cells, but not in macrophages, we measured LCN2 mRNA expression in B16-F1 cells cultured under hypoxic conditions and compared the expression patterns of LCN2 mRNA expression between tumor and normal cells." (PMID 25467539, 2014). "First, while our data strongly implicate tumor cells as the main source of functional LCN2, we cannot definitively exclude contributions from TME-derived sources (e.g., fibroblasts and granulocytes) owing to the lack of conditional LCN2 knockout models." (PMID 41436606, 2025). "GSEA analysis in human datasets also supports our hypothesis, suggesting that LCN2 is a strong negative marker for EMT signaling in GC, in spite of the difference between cancer cells within a single tumor." (PMID 35705840, 2022). "Moreover, another report also indicated that lipocalin 2 was possibly involved in invasion of tumor cells by regulating activity of MMP-9 and MMP-2, but was not apparently related with division and proliferation of tumor cells in SHEEC." (PMID 19077278, 2008).
cancer (373 papers, 2007 to 2026). A tumor composed of atypical neoplastic, often pleomorphic cells that invade other tissues. "Chronic inflammation can lead to cancer, particularly in the colon, and a glycoprotein associated with inflammation, lipocalin‐2 (LCN2), has been implicated in cancer progression." (PMID 39511728, 2025). "It is upregulated in a variety of human diseases and cancers; for example, high levels of LCN2 are associated with breast, pancreatic, thyroid, ovarian, and colon cancer." (PMID 40520011, 2025). "Our study was based on pre‐diagnostic concentrations of LCN2 and focused on cancer development, whereas its role in cancer progression and its utility as prognostic biomarker requires future evaluation." (PMID 39511728, 2025). "Next, we assessed the impact of LCN2 uptake from cancer cells co-cultured with BECN1-deficient adipocytes." (PMID 38744820, 2024). "Several genes, including the transferrin receptor, ferritin heavy chain, ferritin light chain, iron exporter ferroportin, iron regulatory protein 2, and LCN2, have been implicated in the regulation of iron in cancer cells." (PMID 39850877, 2024). "Although LCN2 has been implicated in promoting radioresistance in several cancer types, further research is necessary to fully understand its role and mechanisms across a broader range of tumors." (PMID 39188682, 2024). "LCN2 levels were increased in advanced stages of cancer and they were associated with decreased overall survival." (PMID 36926025, 2023). "Similar findings reported that LCN2 downregulation, limited AT loss and tissue macrophage infiltration in a murine model of cancer cachexia." (PMID 37517520, 2023). "Follow-up studies investigating the potential of LCN-2 as a therapeutic target in cancer cachexia are warranted given the association between its levels and the nutritional status of PDAC patients." (PMID 37006254, 2023). "Lcn-2 was also found to be upregulated in residual cancer cells, found in the host after chemotherapeutic treatment that causes senescence of cancer cells." (PMID 37958332, 2023). "Elevated levels of LCN-2 have been linked to increased cell growth, formation of blood vessels, invasion, and spreading of cancer cells." (PMID 38058391, 2023). "The current study did not look at the correlation between LCN2 level and severity of cancer cachexia, a study we will explore in the future, as will the association of LCN2 levels to body weight loss, and to muscle and fat mass." (PMID 36428623, 2022). "The transporter protein lipocalin-2 (LCN2) also termed neutrophil-gelatinase-associated lipocalin (NGAL) has pleiotropic effects in tumorigenesis in various cancers." (PMID 35053376, 2022). "Others targeted LCN2 using CRISPR/Cas9 which resulted in reduced cancer cell development and raised the susceptibility of MDA-MB-231 cells to cisplatin." (PMID 36077676, 2022). "Recently, the oncological role of LCN2 has been investigated in several types of cancer and has been identified as being negatively associated with EMT signaling in cancer development." (PMID 35705840, 2022). "Neutrophil gelatinase‐associated lipocalin (NGAL), also known as lipocalin 2, siderocalin, 24p3 or uterocalin, is overexpressed in many pathologic conditions, including cancer." (PMID 34104101, 2021). "As overexpression of LCN2 has been associated with increased metastasis of cancer cells, we assessed the effect of LCN2 silencing in the migration and invasiveness potential of IBC cells." (PMID 34445288, 2021). "Utilizing pancreatic ductal adenocarcinoma (PDAC)-associated cancer cachexia models, we demonstrated a clear appetite-regulatory role of LCN2 during the progression of PDAC cachexia." (PMID 34439145, 2021). "The upregulated LCN2 protein expression is positively associated with cancer cell migration and progression in hepatocellular cancer through the hepatocyte activating growth factor receptor/focal adhesion kinase (FAK) signaling pathway." (PMID 34903175, 2021).
cancer (continued). "All these data together indicated that high LCN2 expression was widely associated with immunity in cancers." (PMID 33425761, 2020). "Lipocalin 2 is also named as neutrophil gelatinase-associated lipocalin, has been identified as a potential biomarker in several cancers." (PMID 33473259, 2020). "Elevated LCN2 expression is strongly associated with the acquisition of a metastatic phenotype of cancer cells." (PMID 32575507, 2020). "In this section, we discuss the molecular and biological effects of LCN2 dysregulation in cancer cells, and we explain how the association of LCN2 with iron and the LCN2–MMP-9 interaction contributes to cancer progression." (PMID 32575507, 2020). "So far most studies focused on the role of Lcn-2 in stabilizing matrix metalloproteinase-9 to explain cancer metastasis, linked to extracellular matrix degradation, migration, and invasion." (PMID 28979267, 2017). "LCN2 is also associated with the pathogenesis of various diseases and is upregulated in many types of cancers." (PMID 29285270, 2017). "Dysbalanced LCN2 expression has also been associated with cancer formation and progression in several organs." (PMID 27729871, 2016). "In ovarian solid tumors, LCN2 was associated with cancer differentiation, whereas LCN2 was also proved to be correlated with hepatocarcinoma and lung tumor progression." (PMID 27729871, 2016). "Since the NF-κB/snail signaling pathway is known to enhance the invasiveness and metastatic properties of several types of cancer cells, we sought to investigate the association between this pathway and LCN2 expression." (PMID 27912767, 2016). "Data from our current study showed that T3/TR modulates LCN2, a cancer-associated protein, to promote cancer progression." (PMID 25940797, 2015). "LCN2 is implicated in metabolic reprogramming in various cancers, although its role in TNBC remains unclear." (PMID 41303420, 2025). "Key canonical pathways implicated in cancer following LCN2 knockdown in HER2+ IBC cells." (PMID 40732340, 2025). "LCN2 is associated with UC duration and cancer risk, which may be regulated by IL-17A, IL-22, and TNF-α." (PMID 40153427, 2025). "Furthermore, the oncological role of LCN2 in various cancers has been investigated, revealing its close association with cancer occurrence and development." (PMID 39424639, 2024). "Another hallmark of cancer in which Lcn-2 could play a role focuses on the apoptotic resistance of cancer cells." (PMID 37958332, 2023). "LCN2 is increased in several pathological settings including MS and cancer-associated cachexia." (PMID 37517520, 2023). "The diagnostic value of LCN2 in detecting cancer cachexia is confirmed in patient samples." (PMID 36428623, 2022). "Moreover, LCN2 is highly discussed as a prognostic and/or diagnostic marker in various types of cancer including PCa." (PMID 35053376, 2022). "However, the underlying mechanism and functional role of LCN2 from the perspective of inflammation-associated cancer are still unclear." (PMID 35470375, 2022). "We also hypothesized that the LCN2 gene expression score is associated with aggressive clinical parameters such as pathological grade and cancer stage." (PMID 34072157, 2021). "Moreover, because iron dependency is a hallmark of cancer cells, the association of LCN2 upregulation with the ferroptosis cell-death mechanism must be addressed." (PMID 32575507, 2020). "We determined whether LCN2 expression was associated with the immune infiltration level in various cancers by exploring the coefficient of LCN2 expression and immune infiltration level based on TIMER database." (PMID 33425761, 2020). "In addition, based on the GEPIA dataset, we verified that LCN2 expression had a forceful positive association with advanced cancer stages (P < 0.001)." (PMID 33425761, 2020). "As HIF-1A is firmly associated with the radioresistance of cancer cells, we think that LCN2 might interact with HIF-1A to facilitate the development of a radioresistant phenotype in NPC." (PMID 33604288, 2020).
cancer (continued). "The results showed that LCN2 may indirectly regulate NF-κB activity, but the specific mechanisms underlying their interactions in different cancers need further exploration." (PMID 27912767, 2016). "The up-regulation of LCN2 expression has also been reported in several other carcinomas, such as those in the esophagus, mammary glands and ovary, and LCN2 has been associated with the malignant potential of carcinoma cells." (PMID 27168162, 2016). "The elevated levels of LCN2 tightly associate with the malignance and metastasis of cancer cells." (PMID 25476483, 2015). "Lipocalin 2 (LCN2), a tumor-associated protein, is overexpressed in a variety of cancer types." (PMID 25940797, 2015). "Our results support the prevailing concept that vitamin D status is negatively associated with cancer incidence and mortality and suggest LCN2 may be a potential target against ICC." (PMID 24939880, 2014). "Additionally, while ER stress and Lcn2 are both associated with cancer tumorigenesis, progression, and poor clinical outcome, to date there has been no mechanistic explanation for these correlations." (PMID 21649922, 2011). "Interestingly, Lcn-2 is upregulated in various tissues and fluids in the body, and is linked to several diseases, including ischemic, inflammatory, and metabolic disorders, as well as cancer." (PMID 37958332, 2023). "In addition, the overexpression of LCN2 is associated with radio-resistance and recurrence in NPC patients Thus, the role of LCN2 in carcinogenesis and its underlying mechanism may depend on the various types of cancers." (PMID 36428800, 2022). "In most cancers, LCN2 is upregulated, but the underlying mechanism remains largely unknown." (PMID 36276281, 2022). "Therefore, the role of endogenous, cancer cell-expressed Lcn-2 might be detrimental for ferroptosis susceptibility." (PMID 34069743, 2021). "In addition, previous studies have reported that expression level of lipocalin-2 in cancer patients may be associated with survival." (PMID 33542838, 2021). "Therefore, blocking lipocalin-2 production from macrophages and neutrophils might simultaneously target cancer cells and cancer-associated myeloid cells." (PMID 33679721, 2020). "Moreover, targeting the molecular processes directly associated with LCN2 may indicate an approach to mitigating LCN2-induced cancer development." (PMID 32575507, 2020). "The accumulation of LCN2 in cancer not only contributes to the activation of transcriptional initiation factors but is also regulated by defects in its suppressors." (PMID 40109857, 2025). "LCN2 is a key protein involved in iron metabolism, immune responses, kidney function, inflammation, and cancer development." (PMID 40584713, 2025). "Secreted by a variety of cells, LCN2 is an important biomarker of inflammation, infection, and organ damage and is considered a promoter of cancer progression." (PMID 40520011, 2025). "In recent years, the functions of LCN2 in the metastatic phenotype of malignant tumors have attracted a significant amount of interest." (PMID 40313933, 2025). "Such analyses would provide deeper insights into the mechanisms by which LCN2 exerts its effects on cancer cells and other cell types within the TME." (PMID 41303420, 2025). "Several studies have shown that LCN2 has opposing effects on cancer progression depending on the type of cancer." (PMID 41303420, 2025). "One mechanism that has been identified to facilitate cancer cell survival within the space is through expression of iron-scavenging protein and receptor pair, lipocalin-2 (LCN2) and SCL22A17." (PMID 40100294, 2025). "Here, the genes that were significantly higher expressed in metastatic cells included many genes previously known to be involved in this process in separate cancers, including LCN2 and AGR2." (PMID 39748426, 2025).